ATG5 (autophagy related 5)
Diseases named in the same sentence as ATG5 in open-access papers (continued):
Sharing a sentence is not in itself a finding about the gene and the disease.
ischemia reperfusion injury (1 paper, 2018). Adverse functional, metabolic, or structural changes in ischemic tissues resulting from the restoration of blood flow to the tissue (reperfusion), including swelling; hemorrhage; necrosis; and damage from free radicals. "Similarly, deletion of p21 and autophagy protein 5 (ATG5, which is critically involved in tubular epithelial senescence) aggravated ischemia-reperfusion injury (IRI), leading to increased renal damage and cell death, impaired renal recovery and higher mortality." (PMID 29260442, 2018).
Jaundice (1 paper, 2021). Yellow pigmentation of the skin due to bilirubin, which in turn is the result of increased bilirubin concentration in the bloodstream. "Unexpectedly, we observed that 40% (9 of 22 mice) of YAP-deficient mice developed jaundice within 6 to 8 weeks regardless of Atg7, Atg5, Pten, or Wwtr1 genotype." (PMID 34088666, 2021).
kidney cancer (1 paper, 2023). Primary or metastatic malignant neoplasm involving the kidney. "PIK3CA, IL1R1, HSP90AA1, and ATG5 were significantly lower expressed in tumor tissues (p < 0.05), which were further confirmed by the protein expression profile in kidney cancer downloaded from HPA database." (PMID 36932108, 2023).
laryngeal carcinoma (1 paper, 2025). Carcinoma that arises from the laryngeal epithelium. "Analysis of the TCGA database indicates that autophagy‐related markers in laryngeal cancer tissues, such as ATG5, ATG12, ATG16L, LC3b, Beclin1, mostly exhibit an upregulation trend." (PMID 39893643, 2025). "The data analysis of the TCGA‐HNSC reveals a positive correlation between the expression of CTSL and autophagy‐related markers such as ATG5, ATG7, ATG12, ATG16L and LC3b, suggesting a connection between CTSL and autophagy in laryngeal cancer." (PMID 39893643, 2025).
lentivirus infection (1 paper, 2018). Virus diseases caused by the Lentivirus genus. "The knockdown efficiency was verified by western blots, and the results showed that both ATG5 and ATG7 were significantly reduced after shATG5-1 and shATG7 lentivirus infection, while the knockdown efficiency of shATG5-2 was not satisfied." (PMID 29416002, 2018).
lupus erythematosus (1 paper, 2022). An autoimmune, connective tissue chronic inflammatory disorder affecting the skin, joints, kidneys, lungs, heart, and the peripheral blood cells. "ATG5 rs573775 T* allele seems to influence lupus erythematosus susceptibility, cytokine production and disease features." (PMID 34661876, 2022).
mastitis (1 paper, 2022). Inflammation of breast tissue during lactation or postpartum due to an obstructed duct or infection. "Our results reveal that Z. morio hemolymph alleviates E. coli-induced mastitis via lessening the inflammatory response by regulating the NLRP3 and ATG5/ATG16L1 signaling pathway, as well as repairing the blood-milk barrier." (PMID 36362066, 2022).
medulloblastoma (1 paper, 2022). A malignant, invasive embryonal neoplasm arising from the cerebellum. "For medulloblastoma, MirR-30a inhibited autophagy by reducing beclin 1/ATG5 expression and was linked to increased cell death in a medulloblastoma cell line." (PMID 36197606, 2022).
memory impairment (1 paper, 2023). "LC3B gene promoter regions were hypermethylated in OSA patients, particularly in those with excessive daytime sleepiness, while ATG5 gene promoter regions were hypermethylated in those with morning headache or memory impairment." (PMID 36805797, 2023). "Mean DNA methylation levels over − 108, − 106, − 96, − 86, − 80, − 65, and − 61 CpG sites of the ATG5 gene were increased in SDB patients with memory impairment versus those without memory impairment (3.07 ± 2.33 versus 2.3 ± 0.87%, adjusted p = 0.039)." (PMID 36805797, 2023).
metastasis (1 paper, 2014). The spread or migration of cancer cells from one part of the body (where they first appeared) to another. "ATG-5 expression was significantly associated with depth of wall invasion, TNM stages and distant metastasis of GC (P<0.05), whereas MRP-1 expression was significantly linked with tumor size, depth of wall invasion, lymph node metastasis, TNM stages and differentiation status (P<0.05)." (PMID 25329677, 2014).
myocarditis (1 paper, 2021). Myocarditis is a condition that is characterized by inflammation of the heart muscle (myocardium). "To evaluate the relevance of autophagy in fibrotic heart disorders, we analyzed expression of autophagy-related proteins LC3B, Beclin-1 and ATG5 in endomyocardial biopsies obtained from iDCM patients who developed fibrotic phenotype in comparison to patients with healed myocarditis (no fibrosis)." (PMID 33668422, 2021).
NK/T cell lymphoma (1 paper, 2015). "Other reports also indicated that the expression of HACE1, ATG5, and AIM1 was decreased in NK/T cell lymphoma, although the research is limited." (PMID 26221594, 2015). "The deletion of 6q21 has been identified as the common genetic aberration in NK/T cell lymphoma (20–43%), and the genes located in the region of 6q21, including POPDC3, PREP, PRDM1, ATG5, AIM1, HACE1, and FOXO3, were reasonably considered the affected candidates." (PMID 26221594, 2015).
ocular hypertension (1 paper, 2021). Abnormally high intraocular pressure. "We next utilized ATG5fl/fl mice to determine whether loss of ATG5 in TM (ATG5–/–TM) leads to ocular hypertension." (PMID 33539326, 2021).
Oral leukoplakia (1 paper, 2025). A thickened white patch on the oral mucosa that cannot be rubbed off. "In oral leukoplakia, CD46 expression is upregulated, membrane expression is enhanced in areas of abnormal epithelial hyperplasia, TREM1 expression is elevated, inflammatory cell infiltration is present, and LC3B/ATG5 expression is low." (PMID 41415031, 2025).
ovarian tumors (1 paper, 2025). "Accordingly, ATG5-knockout CAR-T cells exhibited superior and long-lasting control of OVCAR3 ovarian tumors in vivo." (PMID 41279553, 2025). "Here, we demonstrate that targeted disruption of the essential autophagy gene ATG5 metabolically reprograms αFR CAR-T cells for improved function under immune-suppressive conditions, leading to sustained rejection of ovarian tumors in vivo." (PMID 41279553, 2025). "Functionally, ATG5-knockout CAR-T cells maintained high cytolytic activity when assayed in patient-derived ascites in vitro, and exhibited superior and long-lasting tumor control against ovarian tumors in vivo." (PMID 41279553, 2025).
pancreatic adenocarcinoma (1 paper, 2021). "In addition, we analyzed the correlation between YAP and Atg5 expression in the TCGA PAAD (pancreatic adenocarcinoma) database and found a positive correlation between YAP and Atg5 mRNA expression levels (R=0.63, p<0.001)." (PMID 34512171, 2021).
parasite infection (1 paper, 2023). "Cytoprotective autophagy genes, ATG5 and ATG7, are known to be upregulated as a result of PERK/ATF4 pathway activation, which favors cellular survival and parasite infection." (PMID 37152895, 2023).
peritonitis (1 paper, 2021). Inflammation of the peritoneum (tissue that lines the abdominal wall and covers most of the organs in the abdomen). "To investigate this further, we used a zymosan-induced peritonitis model of self-resolving acute inflammation to analyze the impact of EC ATG5 deficiency on the temporal profile of an inflammatory reaction in vivo." (PMID 34363750, 2021). "Similarly, using the inducible mouse model, acute EC ATG5 deficiency promoted increased neutrophil infiltration in the LPS-driven peritonitis model." (PMID 34363750, 2021).
pneumococcal infection (1 paper, 2017). Infections with bacteria of the species streptococcus pneumoniae. "Compared with control siRNA, siRNA to Atg5 significantly inhibited the formation of LC3 puncta following treatment of cells with rapamycin or following pneumococcal infection." (PMID 28399692, 2017). "To explore the mechanism of pneumococcal-induced autophagy further, we tested the effect of silencing the product of the essential autophagy gene Atg5 on autophagy following pneumococcal infection." (PMID 28399692, 2017).
pneumonia (1 paper, 2025). An acute, acute and chronic, or chronic inflammation focally or diffusely affecting the lung parenchyma, caused by an infection in one or both of the lungs (by bacteria, viruses, fungi, or mycoplasma.). "Therefore, we examined the role of ATG5 in AEC2 during P. aeruginosa infection, utilizing a mouse pneumonia model." (PMID 40529614, 2025).
polycystic kidney disease (1 paper, 2021). A usually autosomal dominant and less frequently autosomal recessive genetic disorder characterized by the presence of numerous cysts in the kidneys leading to end-stage renal failure. "In zebrafish models of polycystin-2 deficiency and polycystic kidney disease, co-injection of an atg5 morpholino led to an increase in the cystic phenotype." (PMID 33917666, 2021).
Pompe disease (1 paper, 2013). "The only previous analyses of the Atg genes and glycogen autophagy was in the mouse Pompe disease model, and was limited to mutations in two genes, Atg7 and Atg5, which surprisingly had different effects on the amount of lysosmal glycogen." (PMID 24265594, 2013).
presbycusis (1 paper, 2022). Bilateral hearing loss caused by progressive degeneration of cochlear structures and central auditory pathways, typically associated with the aging process. "In the PPI network, autophagy-related genes ATG5, ATG7 showed the highest node scores in mild presbycusis; whereas MTOR, BECN1 showed the highest scores in severe presbycusis." (PMID 35463035, 2022).
progeria (1 paper, 2022). "For example, overexpression of SA hydroxylase to synthesize NahG can completely inhibit the progeria phenotype of atg2 and atg5, while application of the SA analog BTH (benzothiadiazole) restored the progeria phenotype of these mutants." (PMID 35682913, 2022).
promyelocytic leukemia (1 paper, 2020). "To this end, we used genetically modified human promyelocytic leukemia (HL-60) cells overexpressing ATG5, differentiated toward granulocyte-like cells with all-trans retinoic acid (ATRA) and dimethylformamide." (PMID 32707918, 2020).
prostate adenocarcinoma (1 paper, 2016). "In contrast, in Prostate Adenocarcinoma a large number of copy number deletions were found, mainly in the ATG5 and ZBTB24 gene." (PMID 27256984, 2016). "For instance, in Prostate Adenocarcinoma, frequent copy number deletion for ZBTB24 (13%) and for ATG5 (12%) was observed." (PMID 27256984, 2016).
pseudoexfoliation syndrome (1 paper, 2025). "Our study may gain importance as it is the first study in which Beclin 1, ATG5, ATG6, ATG12, p62, and LC3A/B autophagy markers are examined prospectively in the etiopathogenesis of pseudoexfoliation syndrome, comprehensively and with a control group." (PMID 40925341, 2025).
pulpitis (1 paper, 2021). Inflammation of the dental pulp. "Autophagy related genes such as autophagy related 5 (ATG5), ATG7, microtubule associated protein 1 light chain 3 (LC3) and beclin 1 (BECN1) were increased in pulpitis tissue." (PMID 34434926, 2021).
renal carcinoma (1 paper, 2022). A carcinoma arising from the epithelium of the renal parenchyma or the renal pelvis. "Our results showed that the knockdown of IFI35 increased the expression of autophagy-related genes (Beclin-1, LC3-II, and ATG-5) in renal cancer cells." (PMID 35740527, 2022).
reovirus infection (1 paper, 2017). "Reovirus infection clearly decreased the levels of free Atg5 and increased the conversion of LC3-I to LC3-II, most evident from the reduction in LC3 levels." (PMID 28934149, 2017). "To examine the importance of the autophagy machinery for reovirus infection, we used SV40 transformed MEF cell lines with a knock-out for a specific autophagy-related gene: Atg3, Atg5, or Atg13." (PMID 28934149, 2017). "Our findings that an MOI* of 10 of UV-inactivated reovirus fails to induce LC3 lipidation, Atg5-Atg12 conjugation, or an increase in acidic vesicular organelles demonstrate that a productive reovirus infection facilitates the induction of autophagy." (PMID 28934149, 2017).
respiratory syncytial virus infection (1 paper, 2023). "ATG5 is a key autophagic factor that regulates dendritic cell reprogramming to inhibit respiratory syncytial virus infection." (PMID 38072991, 2023).
restless legs syndrome (1 paper, 2025). A condition that occurs while resting or lying in bed; it is characterized by an irresistible urgency to move the legs to obtain relief from a strange and uncomfortable sensation in the legs. "The receiver operating characteristic curve analyze results and optimal cut‐off levels of ATG3 and ATG5 in patients with restless legs syndrome." (PMID 39776356, 2025).
retinitis (1 paper, 2019). Inflammation of the retina. "Since Atg5 is a key gene regulating autophagy, we bred Atg5flox/flox; Nestin-Cre mice to deeply elucidate the role of autophagy during MCMV retinitis." (PMID 31291924, 2019).
rhabdomyosarcoma (1 paper, 2014). A rare aggressive malignant mesenchymal neoplasm arising from skeletal muscle. "Blocking of autophagy also attenuates cell death caused by the avian influenza A H5N1 virus both in vitro and in vivo, and it is known that knockdown of beclin-1 or Atg5 protects human rhabdomyosarcoma cells from enterovirus 71-induced apoptotic death." (PMID 24490870, 2014).
rickettsial diseases (1 paper, 2019). "More strikingly, Atg5 expression in macrophages contributes to the pathogenesis of rickettsial diseases." (PMID 30297526, 2019). "Thus, Atg5 in macrophages appears to contribute greatly to the progression of rickettsial diseases." (PMID 30297526, 2019).
rosacea (1 paper, 2023). A chronic erythematous skin disorder that affects the face. "In the present study, we found that the mRNA expression of autophagy-related genes Becn1, Atg5, Atg10, and Atg12 was significantly increased in LL37-induced rosacea lesions after topical rapamycin treatment." (PMID 36937834, 2023).
Salmonella Infections (1 paper, 2018). Infections with bacteria of the genus SALMONELLA. "Salmonella infection down-regulated the expression of the following protein biomarkers of autophagy (a catabolic process for stress adaptation of cellular components): Beclin-1, Atg5, Atg12, Atg16, LC3-I and LC3-II." (PMID 30518352, 2018).
severe acute respiratory syndrome (1 paper, 2019). A viral respiratory infection caused by the SARS coronavirus. "However, other studies contradict these findings, showing that Atg5 is not required for MHV, severe acute respiratory syndrome (SARS-CoV) or avian infectious bronchitis virus (IBV) replication." (PMID 31306441, 2019).
spinocerebellar ataxia-25 (1 paper, 2020). "One of them, spinocerebellar ataxia-25 (SCAR25), is caused by a mutation in the autophagy-related 5 gene (ATG5), encoding a protein that is part of the ATG12-ATG5-ATG16L1 complex, which facilitates LC3/GABARAP conjugation." (PMID 32373609, 2020).
systemic sclerosis (1 paper, 2020). A chronic disorder, possibly autoimmune, marked by excessive production of collagen which results in hardening and thickening of body tissues. "An intron SNP in the ATG5 gene (rs9373839) has been associated with systemic sclerosis." (PMID 32377431, 2020).
tauopathy (1 paper, 2023). Neurodegenerative disorders involving deposition of abnormal tau protein isoforms (tau proteins) in neurons and glial cells in the brain. "Overexpression of atg5 in larvae of a zebrafish Parkinson disease model leads to upregulation of autophagy and protected dopaminergic neurons and also upregulated Lc3-II levels and ameliorated pathology in a zebrafish model of tauopathy." (PMID 36310368, 2023). "To investigate whether modulation of autophagy through our inducible system was sufficient to affect disease pathology caused by the accumulation of an aggregate-prone autophagy substrate, we crossed the UAS:atg5 transgenic line to a zebrafish model of tauopathy." (PMID 36310368, 2023).
testicular embryonal carcinoma (1 paper, 2020). A malignant germ cell neoplasm arising from the testis. "In NT-2 cells (a pluripotent human testicular embryonal carcinoma cell line), ATG5-knockdown using small hairpin RNA (shRNA) enhanced the activation of autophagy and reduced the viral replication of JEV RP-9." (PMID 32911775, 2020).
Tinnitus (1 paper, 2023). Tinnitus is an auditory perception that can be described as the experience of sound, in the ear or in the head, in the absence of external acoustic stimulation. "For instance, curcumin promotes the synthesis of Atg5 and Atg7, and this is postulated to underlie most of its activity in counteracting tinnitus." (PMID 38068993, 2023).
tongue squamous cell carcinoma (1 paper, 2023). A squamous cell carcinoma that arises from the tongue. "Additionally, overexpression of Beclin-1 increased the levels of ATG4, ATG5, and LC3-II proteins in tongue squamous cell carcinoma cell lines." (PMID 38028434, 2023).
tularemia (1 paper, 2020). Tularemia is an infection caused by the bacterium Francisella tularensis. "Here, we investigated the role of autophagy in the pathogenesis of tularemia by using transgenic mice deficient in Atg5 in the myeloid lineage." (PMID 33036147, 2020). "Future research on Atg5 functions during the pathogenesis of tularemia should be focused on the elucidation of the inflammatory response regulated by autophagy to gain the much-needed information about this important pathway." (PMID 33036147, 2020). "The data highlight the contribution of Atg5 in the pathogenesis of tularemia in vivo." (PMID 33036147, 2020).
urothelial bladder carcinoma (1 paper, 2022). "To further validate the correlations among ATG5/12, Beclin 1, MMP2, and MMP9 in BC, we analyzed urothelial bladder carcinoma datasets on the GEPIA2 web server." (PMID 35449123, 2022).
vaginal infection (1 paper, 2018). "The data presented here are related to the research article entitled “Knockout of autophagy gene, ATG5 in mice vaginal cells abrogates cytokine response and pathogen clearance during vaginal infection of Candida albicans”." (PMID 29896527, 2018).
vascular tumor (1 paper, 2023). "To explore the mechanisms of autophagy in the regulation of vascular tumor cells, we examined changes in gene expression by transcriptional profiling of Fip200 KO, Atg5 KO, and Atg7 KO cells." (PMID 36813768, 2023).
ZIKV infection (1 paper, 2020). "Besides, specific siRNA strategy confirmed that autophagy can be activated through Atg7-Atg5 and type I IFN signaling pathway upon ZIKV infection, while knocking down of Atg7 and Atg5 effectively decreased the ZIKV clearance in phagocytes." (PMID 32410874, 2020).